MIR1915HG (MIR1915 host gene)
Synonyms: C10orf114; CASC10; bA418C1.3
Gene: Long non-coding RNA gene on chromosome 10 (21,487,597 to 21,497,260, reverse strand). Ensembl gene ENSG00000204682.
Diseases named in the same sentence as MIR1915HG in open-access papers:
MIR1915HG is named in the same sentence as 6 diseases in open-access papers, as found by Europe PMC text mining. Sharing a sentence is not in itself a finding about the gene and the disease.
MIR1915HG shares sentences with these, for which no sentence is quoted: ovarian carcinoma (2 papers); tumor (2); clear cell ovarian carcinoma (1); ovarian tumors (1); prostate carcinoma (1); serous ovarian cancer (1).